TNFRSF14 (TNF receptor superfamily member 14)
Description:
Receptor for four distinct ligands: The TNF superfamily members TNFSF14/LIGHT and homotrimeric LTA/lymphotoxin-alpha and the immunoglobulin superfamily members BTLA and CD160, altogether defining a complex stimulatory and inhibitory signaling network. Signals via the TRAF2-TRAF3 E3 ligase pathway to promote immune cell survival and differentiation. Participates in bidirectional cell-cell contact signaling between antigen presenting cells and lymphocytes. In response to ligation of TNFSF14/LIGHT, delivers costimulatory signals to T cells, promoting cell proliferation and effector functions. Interacts with CD160 on NK cells, enhancing IFNG production and anti-tumor immune response. In the context of bacterial infection, acts as a signaling receptor on epithelial cells for CD160 from intraepithelial lymphocytes, triggering the production of antimicrobial proteins and pro-inflammatory cytokines (By similarity). Upon binding to CD160 on activated CD4+ T cells, down-regulates CD28 costimulatory signaling, restricting memory and alloantigen-specific immune response. May interact in cis (on the same cell) or in trans (on other cells) with BTLA (By similarity). In cis interactions, appears to play an immune regulatory role inhibiting in trans interactions in naive T cells to maintain a resting state. In trans interactions, can predominate during adaptive immune response to provide survival signals to effector T cells (By similarity). (Microbial infection) Acts as a receptor for Herpes simplex virus 1/HHV-1. (Microbial infection) Acts as a receptor for Herpes simplex virus 2/HHV-2.
Synonyms: HveA; TR2; CD270; HVEM; ATAR; LIGHTR
Tractability: Small molecule: a structure with a bound ligand is known. Antibody: UniProt places it where antibodies can reach, with high confidence; its Gene Ontology location is reachable by antibodies, with high confidence; UniProt predicts a signal peptide or a membrane-spanning region; the Human Protein Atlas places it where antibodies can reach.
Gene: Protein-coding gene on chromosome 1 (2,554,244 to 2,565,382, forward strand). Ensembl gene ENSG00000157873.
Subcellular location: Cell membrane
Subcellular location (Human Protein Atlas): Cytosol; Plasma membrane
Pathways (Reactome):
Immune System: Co-inhibition by BTLA; TNFs bind their physiological receptors
Gene Ontology:
Molecular function: cytokine binding; protein binding; receptor ligand activity; ubiquitin protein ligase binding; tumor necrosis factor receptor activity
Biological process: negative regulation of adaptive immune memory response; negative regulation of T cell proliferation; regulation of ERK1 and ERK2 cascade; regulation of T cell tolerance induction to tumor cell; T cell costimulation; cell surface receptor signaling pathway; defense response to Gram-negative bacterium; defense response to Gram-positive bacterium; immune response; immune response-regulating cell surface receptor signaling pathway; negative regulation of alpha-beta T cell proliferation; negative regulation of T cell activation; negative regulation of T cell cytokine production; positive regulation of cytokine production involved in immune response; positive regulation of T cell migration; regulation of B cell proliferation; regulation of type II interferon production; T cell proliferation; tumor necrosis factor-mediated signaling pathway
Cellular component: plasma membrane; plasma membrane protein complex; tumor necrosis factor receptor superfamily complex; external side of plasma membrane
Genetic constraint (gnomAD): Loss-of-function variants: 18 observed, 32.27 expected, observed/expected ratio (o/e) 0.56, 90% interval 0.38 to 0.83. The upper end of that interval is the gene's LOEUF score, 0.83, which puts it in group 3 of 6, group 1 being the genes least tolerant of losing a copy. Missense variants: 352 observed, 376.27 expected, observed/expected ratio (o/e) 0.94, 90% interval 0.86 to 1.02. Synonymous variants: 157 observed, 151.51 expected, observed/expected ratio (o/e) 1.04, 90% interval 0.91 to 1.18.
Cancer hallmarks: proliferative signalling (promotes); escaping programmed cell death (promotes); escaping immune response to cancer (promotes); escaping programmed cell death (suppresses); tumour promoting inflammation; suppression of growth (promotes); escaping immune response to cancer (suppresses); invasion and metastasis (suppresses)
Homologues: Orthologues: chimpanzee TNFRSF14 (98% identical), macaque TNFRSF14 (83% identical), dog TNFRSF14 (50% identical), guinea pig Tnfrsf14 (47% identical), mouse Tnfrsf14 (41% identical), rat Tnfrsf14 (40% identical), zebrafish tnfrsf1b (22% identical), zebrafish cd40 (19% identical), zebrafish tnfrsf11a (18% identical), mouse Tnfrsf10b (18% identical), zebrafish tnfrsfa (17% identical), tropical clawed frog nradd (17% identical), and 3 more. Paralogues in human: TNFRSF1B (22% identical), LTBR (21% identical), TNFRSF6B (21% identical), CD40 (20% identical), TNFRSF11A (20% identical), TNFRSF21 (20% identical), TNFRSF11B (19% identical), NGFR (19% identical), TNFRSF8 (19% identical), TNFRSF25 (17% identical), TNFRSF4 (16% identical), TNFRSF1A (16% identical), and 9 more.
Diseases named in the same sentence as TNFRSF14 in open-access papers:
TNFRSF14 is named in the same sentence as 163 diseases in open-access papers, as found by Europe PMC text mining. Sharing a sentence is not in itself a finding about the gene and the disease. The quoted sentences say what the papers report.
melanoma (30 papers, 2011 to 2025). A malignant, usually aggressive tumor composed of atypical, neoplastic melanocytes. "In cancer, TNFRSF14 upregulation is related to unfavorable survival of melanoma, gastric and colon cancer." (PMID 39085878, 2024). "Two genes, TNFRSF11B and TNFRSF14 that were correlated with the invasion capacity of melanoma cells in our experiments, are part of this prediction system." (PMID 35269787, 2022). "TNFRSF14 was identified as a marker for drug response prediction of melphalan in melanoma, and melphalan was used as the first line of therapy for MM patients in MMRF." (PMID 35401705, 2022). "A significant negative correlation was observed between the relative expression of the TNFRSF14 gene and the invasive capacity of the melanoma cells (R = −0.653, p = 0.041)." (PMID 35269787, 2022). "Both melanoma cell lines showed a comparable viral entry receptor expression profile, with high expression of TNFRSF14 and ITGB8 and low expression of all other genes, which might explain their similar sensitivity to infection with oHSV1-FLT3L." (PMID 40955425, 2025). "In addition, TNFRSF14 is found in tertiary lymphoid structures (TLS) with features that resemble the characteristics of lymph nodes in melanoma." (PMID 39596374, 2024). "Additionally, B7-H2 (CD86) mRNA was found in macrophages, PDCD1 (PD-1) mRNA was present in T cells (as expected), and TNFRSF14 and TNFSF9 mRNAs were observed in both T and melanoma cells." (PMID 40647495, 2025). "Similar to the published data, the TNFRSF14 gene was downregulated in the invasive melanoma cells, which confirmed the negative correlation between TNFRSF14 and the invasion potential." (PMID 35269787, 2022). "Specifically, Herpes Virus Entry Mediator (HVEM, also known as TNFRSF14), a member of the TNF receptor superfamily and thought to be primarily expressed on hematopoietic cells, has also been described to be expressed on melanoma cells." (PMID 33276788, 2020).
lymphoma (23 papers, 2014 to 2025). A malignant (clonal) proliferation of B- lymphocytes or T- lymphocytes which involves the lymph nodes, bone marrow and/or extranodal sites. "Among lymphomas, TNFRSF14 mutation has been reported in follicular lymphoma as well as DLBCL, NOS (EZB) TNFRSF14 mutations have not been reported in mantle cell lymphoma." (PMID 38914869, 2024). "Specifically, mutations and deletions in the TNFRSF14 gene are common in follicular lymphoma (FL), increasing the ability of lymphoma cells to stimulate allogeneic T-cell responses." (PMID 38313801, 2024). "In contrast, the loss of function mutations in the TNFRSF14 gene leads to B-cell autonomous activation as well as extrinsic activation of the lymphoma microenvironment through B and T-lymphocyte attenuator (BTLA attenuator) located on CD4+ T-helper cells." (PMID 34275438, 2021). "It has been reported that TNFRSF14 loss results in microenvironmental changes that support lymphoma growth and the expression of TNFRSF14 plays a role in the pathobiology and prognosis in follicular lymphoma." (PMID 33628738, 2020). "TNFRSF14 exemplifies context-dependency: loss drives lymphoma progression yet may enhance immunogenicity in specific subtypes, necessitating biomarker-driven stratification." (PMID 41048997, 2025). "Studies of diffuse large B-cell lymphomas have revealed that TNFRSF14 changes are described as early driver mutations and accelerated mutations that may occur in the early stages of the disease, considerably earlier than the diagnosis of malignant lymphoma." (PMID 36911389, 2023). "TNFRSF14 alterations reduce HVEM expression, enhancing the alloantigen-presenting capacity of lymphoma B cells and increasing the risk of acute graft-versus-host disease in allogeneic stem cell transplantation." (PMID 41048997, 2025). "Fluorescence in situ hybridization (FISH) analysis showed no rearrangements in BCL2, IRF4, or BCL6, and any deletion in the 1p36 region (TNFRSF14 gene), ruling out other lymphoma types." (PMID 39840177, 2024). "To conclude, our deep sequencing data revealed recurrent mutations in PCFBCL, such as in TNFRSF14, CREBBP and STAT6, thus classifying this lymphoma subtype as a distinct lymphoma entity within the spectrum of cutaneous lymphomas based on molecular grounds." (PMID 36358692, 2022). "In the case with composite EMZL and EBV‐positive DLBCL (case 6), both lymphomas harboured 23 common variants, including mutations in CD274, TET2, and TNFRSF14, and the EBV‐positive DLBCL showed an additional MYC translocation and a further 20 variants over the EMZL component." (PMID 39722652, 2025). "We also found CNA from our assay could also reveal some lymphoma critical genes, such as TNFRSF14 in 1p36.32, TNFAIP3 in 6q23.3, and SETD2 in 3p21.31." (PMID 38313801, 2024). "Finally, mutations in TNFRSF14 (15% in progression cases of GCB COO) and B2M (8% in all progression cases) may promote lymphomagenesis by affecting the immune system response to lymphoma." (PMID 39392347, 2024).
follicular lymphoma (19 papers, 2017 to 2025). Follicular lymphoma is a form of non-Hodgkin lymphoma characterized by a proliferation of B cells whose nodular structure of follicular architecture is preserved. "The TNFRSF14 mutation (c.69+2T>A) found in the lymph node sample has previously been associated with the presence of a tumor-supportive microenvironment in follicular lymphoma." (PMID 41515931, 2025). "The specific TNFRSF14 mutation found in our case (c.472C > T) has been previously reported in follicular lymphoma and DLBCL." (PMID 38914869, 2024). "TNFRSF14 has been associated with proinflammatory factors in tumors and has poor prognosis for follicular lymphoma, while CCL27 has been associated with inflammatory skin diseases like atopic dermatitis, contact dermatitis, and psoriasis, and increased CCL27 secretion is shown to cause inflammation." (PMID 39038097, 2024). "Overall, the mutation profile of the MYC/BCL2/BCL6-TH group is very similar to that of the MYC/BCL2-DH group, characterised by frequent mutations in follicular lymphoma associated genes (BCL2, CREBBP, KMT2D, EZH2, TNFRSF14)." (PMID 38184753, 2024). "Inactivating gene mutation and genomic deletion of tumor necrosis factor receptor superfamily member 14 (TNFRSF14, HVEM) are the characteristic genetic aberrations in EZB-type DLBCL and are associated with transformation of follicular lymphoma." (PMID 36765793, 2023). "Of these, mutations in CREBBP, KMT2D, TNFRSF14 and RRAGC were enriched in follicular lymphoma, and those of BTG2, HLA-A, PIM1, IGLL5, SOCS1, CD83 and SGK1 were enriched in DLBCL." (PMID 33945543, 2021). "Mutations in CREBBP, TNFRSF14 and KMT2D predominated in follicular lymphoma, whereas those in BTG2, HTA-A and PIM1 were more frequent in diffuse large B-cell lymphoma." (PMID 33945543, 2021). "The interaction between HVEM (TNFRSF14) and BTLA (B and T lymphocyte attenuator) is lost in most follicular lymphomas due to an HVEM mutation." (PMID 29046826, 2017). "As expected, mutations in frequent drivers such as CREBBP, KMT2D,TNFRSF14 and RRAGC were more frequent among follicular lymphomas, those of MYC, CCND3 and ID3 prevailed among Burkitt lymphoma and those of BTG2, PIM1, SGK1 and SOCS1 were more frequent among DLBCL." (PMID 33945543, 2021). "Recurrent mutations of genes involved in epigenetic regulation (e.g. KMT2D, CREBBP, and EZH2), JAK-STAT pathway (e.g. SOCS1, STAT6), immune signaling (i.e. TNFRSF14), and BCR/NFKB signaling (e.g. CARD11, CD79B) were previously reported in follicular lymphoma cases." (PMID 35795062, 2022).
breast carcinoma (18 papers, 2013 to 2025). "TNFRSF14 (HVEM) has been observed to have a prognostic impact in breast cancer depending on the level of tumor-infiltrating lymphocytes (TILs), and the worst outcome occurs in patients with high TNFRSF14 expression and low TIL tumors." (PMID 34953500, 2021). "The low expression of PTPN6 was significantly associated with poor overall survival in bladder cancer patients and co-expression with TNFRSF14 (tumor necrosis factor receptor superfamily member 14) had a close correlation in breast cancer." (PMID 34163522, 2021). "Furthermore, PD-L1, CD112, TNFRSF14, TNFSF4, TNFSF18, CD48, and LGALS9 were analyzed for abnormal expression patterns in breast carcinomas." (PMID 34545132, 2021).
glioma (15 papers, 2021 to 2024). A benign or malignant brain and spinal cord tumor that arises from glial cells (astrocytes, oligodendrocytes, ependymal cells). "CD48, an immune checkpoint that has been reported associated with poor prognosis in gliomas, was also down-regulated in T cell population of anti-Tnfrsf14 group samples." (PMID 39085878, 2024). "Indeed, a higher TNFRSF14 expression was significantly associated with a shorter survival for glioma patients and Cox regression models revealed that TNFRSF14 expression was an independent variable for predicting survival." (PMID 36982814, 2023). "Furthermore, the observed disparity in overall survival among glioma cases may be linked to immune heterogeneity based on TNFRSF14 expression levels." (PMID 38560169, 2024). "Meanwhile, transcriptomic analysis of clinical glioma samples showed that a tendency of IFN-γ upregulation accompanied by TNFRSF14 elevation in both LGG and GBM." (PMID 39085878, 2024). "Western blotting analysis with clinical samples disclosed that TNFRSF14 expression elevated with increased glioma grades, which is consistent with a previous report." (PMID 39085878, 2024). "In the brain, Tnfrsf14 transcripts showed a positive correlation with a WHO grade of glioma and TNFRSF14 was significantly increased in a mesenchymal glioma subtype." (PMID 36982814, 2023). "ALKBH5 expression showed positive association with ICP receptors such as TNFRSF14, CD40, CD96 and CD200R1, and ICP ligands such as PDCD1LG2, CD70, TNFSF14, ICOSLG and CD274 in glioma tissues." (PMID 35444654, 2022). "Another immune checkpoint molecule expressed by glioma cells is the herpes virus entry mediator (HVEM; CD270), which is a member of the tumor necrosis factor (TNF) receptor superfamily (TNFRSF14) and found to be expressed on hematopoietic as well as non-hematopoietic cells." (PMID 36480032, 2023). "Notably, we found that the TNFRSF14 (HVEM) level was higher in low-HIF1A-expression lower-grade glioma." (PMID 34305618, 2021). "Additionally, enhanced IFN-γ expression accompanied with TNFRSF14 elevation (High-IFNG & High-TNFRSF14) indicated a shorter survival in glioma than the lower counterpart (Low-IFNG & Low-TNFRSF14), while similar results couldn’t be obtained from PD-L1." (PMID 39085878, 2024). "In addition, the TCGA cohort showed that gliomas with high TNFRSF19 levels had higher amounts of 28 immune checkpoint proteins, such as PD-L1, and lower levels of six immune checkpoint genes compared to those with low TNFRSF14 levels (P < 0.05)." (PMID 38560169, 2024). "Therefore, we hypothesized that high ALKBH5 expression altered the immune microenvironment in the glioma tissues by modulating the expression levels of ICP receptors and ligands such as TNFRSF14, CD40, CD96, PDCD1LG2, CD70 and TNFSF14." (PMID 35444654, 2022).
autoimmune disease (13 papers, 2012 to 2025). A disorder resulting from loss of function or tissue destruction of an organ or multiple organs, arising from humoral or cellular immune responses of the individual to their own tissue constituents. "A Cytoscape network diagram in our study showed that PD-L2 in PDAC is closely related to the expression of PD-L1, CD86, TNFRSF14, PD-1, CD160 and CTLA-4, which are important for the regulation of immunodeficiency and autoimmune diseases." (PMID 31464648, 2019). "Additionally, TNFRSF14 interacts with BTLA to balance immune activation and suppression, which is of great significance in autoimmune diseases and tumor immune evasion." (PMID 41157169, 2025).
bladder cancer (13 papers, 2021 to 2025). "Furthermore, increased expression of TNFRSF14 has been associated with favorable prognosis in bladder cancer and BRCA." (PMID 40433389, 2025). "Oppositely, the overexpression of TNFRSF14 has been reported to repress cell proliferation and induce proliferation in bladder cancer." (PMID 38612406, 2024). "In bladder cancer, the knockdown of TNFRSF14 significantly enhanced the proliferation of bladder cancer cells through the activation of the Wnt/β-catenin-dependent pathway." (PMID 37393364, 2023). "Many compounds with higher sensitivity for treating bladder cancer patients in the low-TNFRSF14-expression group were identified, with obatoclax being a potential drug most likely to treat patients in the low-TNFRSF14-expression group." (PMID 34708131, 2021). "The results showed that in bladder cancer, FLT3LG not only exhibited significant positive correlations with immune checkpoints (CTLA416, IDO117), cytokines and chemokines (TNFSF13B, TNFRSF14, CXCR3, CCL4) but also exhibited the closest association with genes related to HLA18." (PMID 38213738, 2024). "TNFRSF14 induces apoptosis and suppresses proliferation, thus playing a tumor-suppressive role in bladder cancer, which may confer a better prognosis for patients with upregulated TNFRSF14 expression." (PMID 36675305, 2023). "TNFRSF14 served a tumor suppressive role by suppressing tumor cell proliferation and inducing apoptosis in bladder cancer and could act as a new diagnosis and prognostic biomarker for bladder cancer." (PMID 36437961, 2022). "Interestingly, TNFRSF14 is also expressed by tumor cells and TNFRSF14 ligation can inhibit bladder cancer cell proliferation by inducing apoptosis." (PMID 34858395, 2021). "TNFRSF14 plays a role in bladder cancer progression through the Wnt/β-catenin-dependent pathway." (PMID 34708131, 2021). "Finally, TNFRSF14 might exert a tumor suppressor effect in bladder cancer by inducing cell apoptosis and inhibiting proliferation." (PMID 34899848, 2021). "Subsequently, using the bladder cancer (BLCA) cell lines, the role of TNFRSF14 was determined by Western blotting, cell proliferation assay, and 5-ethynyl-20-deoxyuridine assay." (PMID 34708131, 2021). "GSDMB, CLEC2D, APOL2, TNFRSF14, and GBP2 were selected as prognostic genes in bladder cancer patients." (PMID 34708131, 2021).